CD4 (CD4 molecule)
Diseases named in the same sentence as CD4 in open-access papers (continued):
Sharing a sentence is not in itself a finding about the gene and the disease.
lupus (continued). "Moreover, increased intracellular bioavailable iron in CD4+ T cells has also been linked to the pathophysiology of systemic lupus erythematosus (SLE)." (PMID 31824960, 2019). "Unexpectedly, both CD4 and γδ T cells from lupus-prone mice showed deficiency in IFN-γ production." (PMID 31565032, 2019). "CD4+ T cell activation promotes the pathogenic process of systemic lupus erythematosus (SLE)." (PMID 29434598, 2018). "Recently, these pathological characteristics of lupus CD4+ T cells were shown to be caused by aberrant metabolic regulations, and are crucial for spontaneous induction of Tfh cell generation, GC formation, and disease symptoms in lupus-prone mice." (PMID 28045014, 2017). "However, it is widely accepted that loss of B-cell tolerance, in conjunction with CD4 T-cell hyperactivation, is central to lupus pathogenesis." (PMID 28387859, 2017). "Reduced expression of DNA (cytosine-5)-methyltransferase (DNMT)s and global DNA hypomethylation are observed in both human and murine lupus CD4+ T cells, which are associated with increased expression of autoimmune associated genes such as CD40 ligand (CD40L) and TNFSF7 (CD70) in lupus T cells." (PMID 27070142, 2016). "In addition to these linage-specific cytokines and transcription factors, other genes such as HTR1A, LFA-1, CD70, perforin, and CD40L have been found to be demethylated in lupus CD4+ T cells and have been associated with the pathogenesis of SLE." (PMID 25988383, 2015). "Inhibition of such miRNAs expression in CD4+ T cells in patients with lupus caused reverse effects." (PMID 24991086, 2014). "In addition to this common IFN signature, a pathogenic IFN-associated gene signature was detected in the CD4+ T cells and monocytes from the lupus patients." (PMID 24391825, 2013). "Although CD4+ T cells are pathogenic in murine, and apparently in human, lupus, the contribution of individual Th-cell subsets to disease remains unclear, particularly in humans." (PMID 20334681, 2010). "The upregulation of miR-101a is consistent with the previous finding that miR-101a is upregulated in CD4+ T cells from sanroque mice, which develop lupus-like autoimmune syndrome as a result of loss of Roquin mediated-repression of the inducible T-cell co-stimulator (ICOS)." (PMID 21170274, 2010). "T follicular (TFH) and peripheral helper (TPH) cells have been increasingly recognized as a pathogenic subset of CD4 T cells in systemic lupus erythematosus (SLE)." (PMID 38550577, 2024). "Several genes sensitive to DNA methylation and are linked with systemic lupus erythematosus (SLE) and other autoimmune illnesses were discovered to be hypomethylated in lymphocytes, especially CD4+ T cells." (PMID 38510251, 2024). "Systemic lupus erythematosus (SLE) is a complex autoimmune disorder characterized by the loss of normal CD4+ T cell activity balance." (PMID 39340806, 2024). "Additionally, the unique ac4C-related transcripts revealed new dysregulated ac4C mRNAs that may be translated in lupus CD4 + T cells and linked to important immunological and inflammatory responses." (PMID 39294397, 2024). "Furthermore, lupus-prone mice display signaling deficiencies in CD4+ T cells." (PMID 38137363, 2023). "Furthermore, the B6.Nba2 mouse model of lupus develops a disease dependent on CD4+ T cells, as MHC-II-deficient mice are protected from disease, suggesting that IFN-I stimulation of CD4+ T cells could be involved in disease pathogenesis." (PMID 35055071, 2022). "Furthermore, IFNγ production by CD4+ T cells is enhanced by several lupus associated stimuli." (PMID 33519824, 2020). "Furthermore, demethylating CD4+ T-cells with DNA methylation inhibitors such as 5-azaC, Pca, and Hyd causes autoreactivity and injecting the autoreactive cells into syngeneic recipients causes a lupus-like disease." (PMID 31766160, 2019). "Lupus nephritis (LN), a challenging organ manifestation in SLE, is characterized by the infiltration of pathogenic CD4+ T cells into the inflamed kidney." (PMID 31614462, 2019).
lupus (continued). "In systemic lupus erythematosus (SLE), perturbed immunoregulation underpins a pathogenic imbalance between regulatory and effector CD4+ T-cell activity." (PMID 31781109, 2019). "Summary of differential deoxyribonucleic acid (DNA) methylation patterns in naïve CD4+ T cells associated with systemic lupus erythematosus (SLE), disease severity, and organ-specific manifestations." (PMID 29740453, 2018). "Further, CD4+ T cells treated with these drugs or other DNA methylation inhibitors such as 5-azacytidine become autoreactive and cause lupus-like anti-DNA antibodies in non-lupus prone mice, and anti-DNA antibodies and immune complex mediated glomerulonephritis in lupus-prone mice." (PMID 28620656, 2017). "Over-expression of miR-29b insystemic lupus erythematosus (SLE) has been linked to hypomethylation of DNA in CD4+ T cells." (PMID 27570566, 2016). "The aberrant activity of CD4+ T cells in patients with systemic lupus erythematosus (SLE) is associated with DNA hypomethylation of the regulatory regions in CD11a and CD70 genes." (PMID 24082908, 2013). "In the (NZBxNZW) F1 mouse model for lupus we previously found that a progressive and self-amplifying disruption of Treg homeostasis due to an acquired IL-2 deficiency essentially contributes to the hyperactivity of conventional CD4+ T cells (Tcon) and disease development." (PMID 23446139, 2013). "Systemic lupus erythematosus accounted for the largest share of papers (fifteen studies) and consistently centered on DNA hypomethylation or histone acetylation defects in CD4+ T cells." (PMID 41376628, 2025). "Here, we extend these studies by analyzing changes in CD4+ T cell glucose metabolic capacity in lupus patients with moderate and severe activity status following hUC‐MSCs treatment." (PMID 40801323, 2025). "In lupus, CD4+IFN-γ+ T cells (Th1 cells), the number of which is increased, are the major sources of systemic IFN-γ." (PMID 40048256, 2025). "In human lupus patients, naïve CD4+ T cell cluster frequencies were distorted, with the TIFN cluster expanding proportionately with disease score." (PMID 39866877, 2025). "Inhibition of HSP90AA1 exhibited a decrease protein expressions of glucose enzymes, HSP90AA1, PI3K, and p‐AKT in splenic CD4+ T cell of lupus‐prone mice." (PMID 40801323, 2025). "In this study, we focused our study on changes in glucose metabolism of CD4+ T cells and inflammatory factors expression following hUC‐MSCs treatment to identify the metabolic mechanism of hUC‐MSCs therapy on CD4+ T cell cytokine secretion in lupus." (PMID 40801323, 2025). "Our study reveals that hUC‐MSCs treatment proportionally restores the CD4+ T cell glucose metabolic activity in lupus patients with disease progression." (PMID 40801323, 2025). "We next investigated the intrinsic role of glutaminolysis in CD4+ T cells in lupus with the Gls1fl/fl CD4-Cre system (Gls1 CD4-KO), which has been previously used to investigate glutaminolysis in Th1 and Th17 cells." (PMID 40956613, 2025). "Overall, we confirmed that BTN3A1 inhibition of the IL‐38‐ferroptosis axis affects CD4+ T cell biological activity and is involved in lupus pathogenesis." (PMID 40959207, 2025). "The construct was used in a humanized murine lupus model resulting in a reduction in splenomegaly, CD4+ cell counts, plasmablasts and B cells." (PMID 40481370, 2025). "Studies have shown that NAT10 and global ac4C levels are downregulated in CD4+ T cells from patients with systemic lupus erythematosus (SLE), with abundant ac4C peaks in mRNA CDSs and 3′ UTR regions, indicating dysregulation of ac4C modifications in SLE." (PMID 39764566, 2025). "While obinutuzumab has been a first‐line therapy for follicular lymphoma, a preclinical animal trial in lupus mice confirmed that obinutuzumab greatly relieved renal damage, lowered anti‐RNA autoantibodies and activated CD4 T cells compared with RTX." (PMID 40491969, 2025).
lupus (continued). "For instance, total glucosides of paeony promote the generation of Tregs by inducing Foxp3 expression through reducing the DNA methylation level of the Foxp3 promoter in lupus CD4 T cells." (PMID 41458964, 2025). "Defective DNA methylation and CD70 upregulation in CD4+ T cells were seen in lupus‐prone MRL/lpr mice." (PMID 40976999, 2025). "The downstream consequence of diminished DNMT1 activity is global DNA hypomethylation in CD4+ T cells from lupus patients." (PMID 41376628, 2025). "Enhanced glycolysis, or the conversion of glucose to pyruvate, is a characteristic shared by CD4+ T cells from lupus‐prone animals and individuals with SLE." (PMID 40976999, 2025). "In various autoimmune diseases, CD4+ T cells from patients with lupus exhibit a hypomethylation profile." (PMID 40533455, 2025). "As reported by others, we confirmed that the inhibition of glutaminolysis reduced glycolysis in CD4+ T cells, but here we showed it affected specifically lupus Tfh cells with little effect in healthy Tfh cells." (PMID 40956613, 2025). "In MRL/lpr mice, systemic administration of apoVs reduced lymphoproliferation, decreased IFN-γ+ CD4+ T cells, increased Foxp3+ regulatory T cells, and alleviated the inflammatory activity of lupus and arthritis." (PMID 40332512, 2025). "Promotion of CD4+ T cells activation and imbalanced differentiation of effector T cells was related to aggravation of the lupus‐like features." (PMID 40959207, 2025). "Glutaminolysis is enhanced in T cells of patients with lupus and in Tfh cells, a critical subset of CD4+ T cells that provide help to autoreactive B cells, in lupus mice." (PMID 40956613, 2025). "With both C1q deficiency and irregular CD4 + T-cell signaling playing major roles in SLE development, we investigated the interaction of these two factors to gain new insight into lupus progression." (PMID 40429614, 2025). "We investigated the metabolic mechanism whereby hUC‐MSCs modify CD4+ T cell cytokine secretion in lupus." (PMID 40801323, 2025). "Similar to coronary atherosclerosis, decreased RFX1 expression in CD4+ T cells from patients with systemic lupus erythematosus induces histone H3 acetylation and reduces DNA methylation and H3K9 trimethylation, leading to IL-17A overexpression." (PMID 41425715, 2025). "Some studies have demonstrated that GLS2 protein expression is downregulated in CD4+ T cells from lupus-prone MRL/lpr mice and SLE patients." (PMID 39388708, 2025). "This was confirmed in our in vivo experiments in which BTN3A1 increased the proportion of CD4+ T cells (including a higher percentage of Th1, Th2, Th17 cells and a lower percentage of Treg cells) in the lupus‐like mice." (PMID 40959207, 2025). "HIF1α has been reported to be upregulated in the kidneys of LN patients and in peripheral CD4+ T cells of lupus patients; however, the mechanisms behind the abnormal levels of HIF1α are still unclear." (PMID 40728997, 2025). "Previous studies also reported increased CD153+ CD4+ T cells in the spleens and adipose tissue of aged mice, high fat diet-fed mice and mouse models with lupus." (PMID 40534878, 2025). "The most striking enrichments were autoimmune‐related signatures (e.g., systemic lupus erythematosus CD4 T cells vs. B cells; FDR = 1.4 × 10−68), underscoring a consistent association between 47,XXY and altered immune epigenetic profiles." (PMID 41025454, 2025). "Inhibition of HSP90AA1 exhibited a decrease mRNA levels of glucose enzymes, Hsp90aa1, Pi3k, and Akt in splenic CD4+ T cell of lupus‐prone mice." (PMID 40801323, 2025). "We recently investigated the role of glutaminolysis in the expansion of CD4+ Tfh cells and germinal center (GC) B cells leading to the production of autoantibodies in the lupus-prone triple congenic (TC) B6.Sle1." (PMID 40956613, 2025).
lupus (continued). "Pvt1 suppression skews immunity toward Th1/Treg dominance (pro-inflammatory resolution), while its overexpression exacerbates Th2/Th17 bias (pro-inflammatory amplification), directly disrupting CD4+ T cell homeostasis in lupus." (PMID 40493320, 2025). "A recent study also reported increased IFN responsiveness in naïve CD4+ T cells from pediatric lupus patients." (PMID 39866877, 2025). "Follicular helper T cells (Tfh), a critical subset of CD4+ T cells in lupus, are characterized by high expression of CXCR5, PD-1, interleukin-21 (IL-21), and the specific transcription factor BCL6." (PMID 40989817, 2025). "In a mouse model of systemic lupus erythematosus, a systemic autoimmune disorder, long-term administration of CTLA4Ig significantly decreased CD4+ T cell numbers and reduced the population of auto-reactive B cells producing anti-DNA antibodies." (PMID 40660327, 2025). "Cell communication analysis revealed altered interactions between effector CD4+ T cells and B cells in lupus mice compared to controls, with DHA treatment reducing these interactions." (PMID 40728997, 2025). "The second dataset included filtered naïve CD4+ T cells of only healthy controls in a previously published lupus dataset, has groups denoted as aHD for adult and cHD for pediatric healthy controls." (PMID 39866877, 2025). "This is evidenced by the exaggerated inflammatory response in lupus, involving the elevated proliferation of CD4+ T-cells, excessive activation of B-cells and dendritic cells, and altered cytokine secretion at inflammation sites." (PMID 40429614, 2025). "CD4+ T cells from patients with SLE exhibit several abnormalities that contribute to lupus pathogenesis, including a decrease in naive CD4+ T cells, an increase in Tfh cells, and abnormal TCR responsiveness." (PMID 40693461, 2025). "In it, it was demonstrated that the treatment with MMF of patients with systemic lupus erythematosus reduced the absolute count of CD4+ T cells, CD8+ T cells and B cells in peripheral blood by about 49%, 35% and 48%, respectively." (PMID 39845953, 2024). "Rather, differential chromatin accessibility in lupus results from widespread changes to accessibility within all subpopulations of CD45RA+CD27+CD4+ T cells, including true naive Th cells." (PMID 39688922, 2024). "We defined the transcriptome and epigenome of multiple CD4+ T cell populations from patients with lupus and healthy individuals." (PMID 39688922, 2024). "Single-cell transcriptome profiling revealed an exhausted regulatory CD4 + T-cell subset in systemic lupus erythematosus." (PMID 39294397, 2024). "Meanwhile, CD4+ T cells from SLE patients exhibited metabolic abnormalities similar to that from lupus-prone mice, which indicated that both aerobic glycolysis and OxPhos contributed to the hyperactivity of CD4+ T cells in SLE." (PMID 39039306, 2024). "Research in LN patients has shown that iron accumulation within T cells promotes gene transcription by driving DNA hydroxymethylation and demethylation, thereby facilitating CD4+ T cell activation, which exacerbates lupus manifestations." (PMID 39726588, 2024). "The presence of CD3/CD28 activated CD4+ T cells dramatically up-regulated PD-L1 expression on basophils, as observed in vivo in the lupus-like context." (PMID 38649353, 2024). "IL-2 limits CD4 Tfh cell and GC formation and also promotes several downregulatory mechanisms of potential importance in lupus, including formation and/or maintenance of CD8 CTL, Th1 CD4 T cells, and CD4 Tregs." (PMID 38915570, 2024). "CD127 restitution and TIGIT co-expression on nascent CD4 + and CD8 + memory T cells correlate with the reduction of pathogenic T cell subsets and are valuable for assessing and predicting lupus treatment efficacy." (PMID 38650001, 2024). "The accumulation of mitochondria in CD4+ T cells of B6/Rab4AQ72L and B6.TC/Rab4AQ72L mice is consistent with a role for Rab4A in depleting Drp1 and thus limiting mitophagy in lupus T cells." (PMID 38519468, 2024).
lupus (continued). "As shown in other human studies and previous reports, increased TFH cell proportions among CD4+ T cells and basophil accumulation were observed in both lupus-like mouse models in blood, spleen, and lymph nodes." (PMID 38649353, 2024). "Research on systemic lupus erythematosus showed that effector memory T cells in the CD4+ and CD8+ T-cell subsets increased after RTX treatment, while a decreasing trend was observed for naïve T cells." (PMID 38448810, 2024). "The frequency of circulating CD4+CXCR5+ T cells was found to increase in systemic lupus erythematosus, Sjögren's syndrome, rheumatoid arthritis, juvenile dermatomyositis, Graves’ disease, and myasthenia gravis." (PMID 38383066, 2024). "Previous research has shown that the activation of NFAT1 signaling is primarily responsible for the elevated expression of CD154 on CD4+ T cells in systemic lupus erythematosus." (PMID 39079960, 2024). "One study specifically showed that IL-17-deficient mice are protected against lupus; this finding was associated with a reduced frequency of DNT cells and, conversely, with the expansion of CD4+ regulatory T cells." (PMID 38255272, 2024). "PBMC-derived CD4+ T cells from patients with multiple sclerosis (MS), Sjögren's syndrome (SjS), ulcerative colitis (UC), and systemic lupus erythematosus (SLE) showed lower TNFSF8 expression levels than those from the control groups." (PMID 39170389, 2024). "TGP increased the number and percentage of Treg cells in lupus CD4+ T cells and increased IFN-γ and IL-2 expression." (PMID 37511964, 2023). "Mycophenolic acid (MPA) can up-regulate the global acetylation status of histone H3/H4 by regulating HAT and HDAC in CD4(+)T cells in lupus." (PMID 37261347, 2023). "Similar therapeutic efficacy was observed when CD4+Lrig1+ T cells were adoptively transferred into lupus-prone (NZB/NZW) F1 mice." (PMID 37666819, 2023). "The anomalous alterations in histone modifications of CD4+ T cells potentially play a role in the pathogenesis of lupus by upregulating CD70 expression." (PMID 38235133, 2023). "TGP causes down-regulated Foxp3 promoter methylation levels, thus increasing the expression of Foxp3 in lupus CD4+ T cells." (PMID 37511964, 2023). "A meta-analysis showed that a lower percentage of Tregs/CD4+T cells was observed in patients with active lupus compared to those with inactive SLE." (PMID 37771588, 2023). "For example, Helios was expressed more strongly in CD4+ Treg and Tconv populations in two murine models of lupus, yet more weakly by γδ T, DN T, and Ly49+ CD8+ Treg cells during the progression of the disease." (PMID 38203623, 2023). "In lupus murine models, CD4+Foxp3+ Treg cells reduced the suppressive capacity against T cell proliferation, and adoptive transfer of Treg cells leads to lupus disease suppression and remission." (PMID 37771588, 2023). "Some scholars have studied lupus mice and found that the number of CD4 + CD25 + Foxp3 + Treg cells decreased in the advanced stage of the disease, suggesting that the decrease in the number of cells is related to the pathogenesis of lupus mice." (PMID 37474625, 2023). "The therapeutic activity of CD4+Lrig1+ T cells was comparable to that of methylprednisolone, a clinically used lupus medication." (PMID 37666819, 2023). "This study aims to understand the molecular mechanism underlying the DNA hypomethylation and the upregulation of Dlk1-Dio3 miRNAs in lupus CD4+ T cells." (PMID 38153351, 2023). "Further, we demonstrated the upregulation of Tet1, Tet2, and Tet3 genes in CD4+ T cells of other two lupus strains, B6/lpr and B6.sle123." (PMID 38153351, 2023). "Compared with healthy controls, lupus patients showed elevated levels of H3K27me3 in CD4+ T cells, a process facilitated by EZH2, a histone methyltransferase." (PMID 38235133, 2023).